AFP (alpha fetoprotein)
Diseases named in the same sentence as AFP in open-access papers (continued):
Sharing a sentence is not in itself a finding about the gene and the disease.
infection (continued). "The expression of mRNAs for Cadherin, Albumin, GstA4 and AFP were significantly increased 20 and 40 days after the first infection and those for MaoA and MaoB were augmented to some extent." (PMID 28352551, 2016). "Multivariate Cox regression analysis revealed that HCV non-infection (P = 0.0375) and low AFP (P = 0.0114) correlated significantly with RFS." (PMID 26160842, 2015). "We first examined the inhibition efficiency of artificial microRNAs on target mRNAs in these cells 48 h after infection by the recombinant adenovirus Ad/AFP-Casp-AFP-amiR." (PMID 25924900, 2015). "The univariate analysis revealed that recipient age, sex, bilirubin levels, AFP levels, time of operation, duration of mechanical ventilation, and length of stay in the ICU were identified as potential variables associated with post-LT infection (P < 0.10)." (PMID 40492761, 2025). "AFP and CK-18 were upregulated after of infection for 2 weeks." (PMID 38739590, 2024). "In the PRV- and mock-infected groups, 241 differentially expressed proteins (DEPs) were identified, 162 upregulated and 79 downregulated proteins at 24 h post-infection (hpi), among which AFP, Vtn, Hsp40, Herc5, and Mccc1 may play important roles in PRV propagation." (PMID 34680952, 2021). "However, important indexes associated with outcomes such as age, AFP, and infection are not included in these models." (PMID 34222294, 2021). "Also, it is considered highly sensitive and as the infection to AFP ratio declines with the increasing use of IPV and planned, successive withdrawal of different types of OPV, expanded deployment of ES should ensure higher likelihood of detecting the silent circulation of PV." (PMID 30376094, 2018). "We found that markers of liver inflammation AST, ALT, AFP, GGT were statistically significantly higher in patients with genotype 1 infection, although the actual differences were small." (PMID 32433676, 2020). "We examined the association between HCV genotypes and liver enzyme (AST, ALT, bilirubin, GTT, AFP) and HCV RNA measurement in acute, chronic HCV mono-infection and HIV-HCV coinfection." (PMID 30865664, 2019). "Concomitant infection with HBV and impairment from hepatic sclerosis in the hepatic parenchyma lead to an increase of AFP levels." (PMID 23210562, 2012). "MDCR score = 0.125*PT-0.001*alpha-fetoprotein + 0.007*TBIL-0.15*PTA + 0.022*Age + 0.073*BUN + 0.075*WBC + 1.096*Infection (noted as 1, not noted as 0) + 1.194*HE (noted as 1, not noted as 0)." (PMID 36930107, 2023). "FER score = 0.01*HB-0.001*alpha-fetoprotein + 0.001*TBIL-0.019*PTA + 0.026*Age + 0.062*blood urea nitrogen (BUN) + 0.061*WBC + 0.996*infection (noted as 1, not noted as 0) + 1.127*HE (noted as 1, not noted as 0)." (PMID 36930107, 2023). "For AfP, the lack of an effect on the mating percentage suggests that the infection does not affect flies’ mating propensity for either sex." (PMID 31797888, 2019). "In the other hand, AFP level can be elevated in patients with chronic liver disease with high degree of hepatocytes regeneration such as HCV-infection that show a high level of AFP in absence of malignancy." (PMID 22690340, 2012). "Furthermore, multivariate analysis confirmed that low FAM96B expression (HR: 2.05; 95% CI: 1.21-3.44; P = .006) was independently associated with OS in individuals with HCC, regardless of age, gender, HBsAg infection, and AFP levels." (PMID 39697039, 2024). "We assumed that this was probably because the infection of HBV could cause damage to hepatic cells, leading to the elevation of AFP, which seemed not to contradict the conclusion that HBsAg(+) inhibited SLM in CRC patients." (PMID 36910607, 2023). "Transduction with Ad-CMV-DN-PP2Acα induced overexpression of PP2Ac in L-02, SK-Hep-1, HepG2 and Hep3B cells, whereas infection with Ad-AFpg-DN-PP2Acα only led to the overexpression of PP2Ac in AFP-positive HepG2 and Hep3B cells, but not in AFP-negative L-02 or SK-Hep-1 cells." (PMID 23173703, 2012).
infection (continued). "Statistical analysis here revealed no influence of age, sex, infection time, etiology, ALT, AST, total bilirubin, prothrombin time and AFP on thioredoxin in HCC patients (P > 0.05, respectively)." (PMID 25871387, 2015). "Statistical analysis here revealed no influence of age, sex, infection time, etiology, family history, HbsAg, HBV or HCV copies, ALT, AST, TB, PT and AFP on TrxR in HCC patients (P > 0.05, respectively)." (PMID 25970775, 2015). "Regarding AFP-negative HCC cases, hsa-miR-21-5p/hsa-miR-199a-5p and has-miR-155-5p/hsa-miR-199a-5p ratios can be used to better identify HCC development in LC patients with CHCV-G4 infection, with higher sensitivities." (PMID 36834570, 2023). "However, other factors, such as age, sex, infection time, etiology, HbsAg, hepatitis B virus copies, alanine aminotransferase (ALT), aspartate aminotransferase, total bilirubin, prothrombin time, and AFP were all detected to have none apparent influence regarding serum Hs-CRP level (all P > 0.05)." (PMID 26656354, 2015).
gastrointestinal tumors (35 papers, 2015 to 2025). "Among the results of gastrointestinal tumor marker assays, alpha-fetoprotein (AFP) was measured at 8.09 μg/L, which is above the reference interval (0-6.66 μg/L)." (PMID 41333221, 2025). "AFPGC is designated by the World Health Organization’s (WHO) classification of digestive system tumors as an infrequent form of GC with elevated AFP expression." (PMID 39902132, 2024). "Nevertheless, serum CEA demonstrated superior predictive ability for survival compared to other serum gastrointestinal tumor markers, including AFP, CA19-9, as well as CA72-4, with AUC values of 0.758, 0.533, 0.619 and 0.604, respectively." (PMID 39902132, 2024). "It is considered that the increase of alpha feto protein (AFP) level is closely related to liver cancer, and the significant rise of carcinoembryonic antigen (CEA) level is linked with digestive system tumors." (PMID 35127494, 2021). "NOX1 levels were also correlated with the levels of α-fetoprotein (AFP), a major serum protein produced by the fetal liver which is repressed upon hepatocyte maturation but reactivated in liver malignancies." (PMID 25806803, 2015). "Additionally, malignancies such as gonadal and gastrointestinal tumors can also contribute to increased AFP levels." (PMID 38952558, 2024). "Finally, we used 200 ng/mL and 40 mAU/mL as cut-off values for AFP and DCP levels at baseline, respectively, as suggested by the Asia Pacific Association for the Study of the Liver HCC guideline." (PMID 32218295, 2020). "However, there were serious limitations with AFP, such as low sensitivity, false-negatives, and false-positives, owing to conditions such as pregnancy and certain gastrointestinal tumours." (PMID 33312206, 2020). "Moreover, whether widely used biomarkers such as CEA, CA19-9, CA-125 and AFP in digestive system tumors can provide more information about the spread of EHMs in patients with CRLMs remains unclear." (PMID 39898242, 2025). "The presence of digestive system tumors and the occurrence of bone metastases may lead to increasing carbohydrate resistance, such as the indexes of alpha-fetoprotein (AFP), carcinoembryonic antigen (CEA), prostate specific antigen (PSA), CA199, CA724, CA50, and CA242." (PMID 37404755, 2023). "As for the serum levels of the most commonly used gastrointestinal tumor markers such as CA19‐9, CA 125, AFP, CA 242, and CEA, our study presented a quite interesting result." (PMID 34837350, 2022).
liver (15 papers, 2014 to 2024). "A shorter OS was associated with ECOG PS 2, peritoneum metastasis, the presence of previous immunotherapy, Child‐Pugh stage B, and high alpha‐fetoprotein (AFP) concentration." (PMID 35403359, 2022). "Factors including ECOG PS, lung metastasis, peritoneum metastasis, previous immunotherapy, Child‐Pugh stage, AFP concentration, and macrovascular invasion were significantly associated with OS by univariate analysis." (PMID 35403359, 2022).
benign tumors (12 papers, 2013 to 2024). "Conversely, in children older than 1 year, a normal AFP level often suggests a benign tumor." (PMID 39606696, 2024). "Expectedly, no significant elevations of serum markers were observed in benign tumors, since AFP, bHCG and M371 represent specific products of embryonic tissues that are only present in GCTs." (PMID 36869885, 2023). "Normal AFP and HCG levels are also suggestive of benign tumors." (PMID 31694673, 2019). "All the patients were negative for CEA and AFP, indicating that VTs are benign tumours." (PMID 34373472, 2021). "No patients with nontumorous masses or benign tumors had abnormal serum AFP or CEA levels." (PMID 23826706, 2013).
inflammation (6 papers, 2014 to 2025). Aberrant reaction of the microcirculation characterized by movement of fluid and leukocytes from the blood into extravascular tissues. "Our data showed the clinical significance of serum AFP levels in diagnosing liver inflammation and fibrosis." (PMID 25128299, 2014). "In addition, high serum AFP may be a marker of liver inflammation in patients with chronic liver disorders." (PMID 29930697, 2018).
genetic diseases (5 papers, 2022 to 2026). "In young children, elevated AFP levels can mask the presence of certain genetic diseases, liver regeneration in chronic diseases, and tumorigenesis processes." (PMID 37686577, 2023). "In addition to assessing genetic diseases, amniocentesis can be used to assess the presence of intra-amniotic or fetal infections by culture or polymerase chain reaction or to assess neural tube defects by measuring alpha-fetoprotein and acetylcholinesterase in amniotic fluid." (PMID 36233412, 2022). "AFP was 20.58ng/L, and he has no family history of genetic disorders." (PMID 39723391, 2024). "AFP was exceeding 800ng/L, and he has no family history of genetic disorders." (PMID 39723391, 2024). "Alpha-fetoprotein (AFP) was 46.51ng/L, and he has no family history of genetic disorders." (PMID 39723391, 2024).
metabolic disease (4 papers, 2017 to 2023). A congenital disorder (due to inherited enzyme abnormality) or acquired (due to failure of a metabolically important organ) disorder resulting from an abnormal metabolic process. "We hypothesized that the presence of AFP in metabolic diseases with hepatic involvement may reflect regenerative activity within a damaged liver." (PMID 35455589, 2022).
gynecological tumor (3 papers, 2019 to 2024). "Serum gynecological tumor markers, including alpha-fetoprotein (AFP), carcinoembryonic antigen (CEA), cancer antigen (CA) 199 (CA199), CA153, and CA125, were within normal levels." (PMID 38419118, 2024). "It is reported that 7.5% of gynecological tumors were positive for expression of AFP and 22.6% were positive for CA125." (PMID 31626091, 2019). "Hence, AFP and CA125 should not be the specific criteria for diagnosing gynecological tumors." (PMID 31626091, 2019).
hematological malignancies (3 papers, 2022 to 2024). "We stress that this diagnosis should be taken into account in the absence of other single hepatic lesions or primary tumors of hematological disorders, particularly when there is a normal AFP level." (PMID 37482619, 2023). "Therefore, this diagnosis should be taken into account in the absence of other single hepatic lesions or primary tumors of hematological disorders, especially when the AFP level is normal." (PMID 37482619, 2023).
gastrointestinal disease (2 papers, 1987 to 2023). A disease that occurs in the gastrointestinal system, excluding the hepatobiliary system. "Although AFP is the most commonly used biomarker in HCC, its reliability for screening and diagnosis remains suboptimal, as elevated APF level is also seen in gastrointestinal disease or benign liver disease." (PMID 37059591, 2023). "Serum levels were determined in 434 patients with benign and malignant gastrointestinal diseases and compared with the serum concentrations of carcinoembryonic antigen (CEA) and alpha-fetoprotein (AFP)." (PMID 2441731, 1987).
intestinal diseases (1 paper, 2022). "In addition, alpha-fetoprotein (AFP), IGK protein, and collagen alpha-1 (I) chain precursor (COL1A1) were also used as biomarkers for some intestinal diseases." (PMID 36204290, 2022).
mitochondrial disease (1 paper, 2019). "Among the tests for body fluids, elevated lactate and pyruvic acid in mitochondrial diseases, elevated alpha‐fetoprotein, and decreased immunoglobulin A in AT were described as contributory to the diagnosis." (PMID 31469254, 2019).
neurologic diseases (1 paper, 2016). "Certainly, further research about the role of elevated serum AFP in neurologic diseases is warranted in large sample." (PMID 27644330, 2016).
AFP also shares sentences with these, for which no sentence is quoted: portal hypertension (51 papers); cerebellar ataxia (11); Hepatic steatosis (11); alcoholic liver diseases (9); cardiovascular disease (8); non-small cell lung carcinoma (6); lymphopenia (5); coronary heart disease (4); Dystonia (4); mesenchymal hamartoma (4); peripheral neuropathy (4); placental abruption (4); renal failure (4); Sensorimotor neuropathy (4); digestive system cancer (3); esophageal (3); gallstones (3); heart disease (3); hemangioendothelioma (3); Liver abscess (3); malaria (3); neurodegenerative disease (3); neuropathy (3); non-alcoholic fatty liver disease (3); prostate (3); reproductive system tumors (3); synovial sarcoma (3); syphilis (3); testicular neoplasm (3); tuberculosis (3).
A further 253 diseases each share a sentence with AFP in 2 papers or fewer.